CXCR2 (C-X-C motif chemokine receptor 2)
Diseases named in the same sentence as CXCR2 in open-access papers (continued):
Sharing a sentence is not in itself a finding about the gene and the disease.
breast tumor (19 papers, 2012 to 2025). "Upregulation of Ccl19, Ccl20 and chemokine (C-X-C motif) receptor (Cxcr) 2 has also been associated with breast tumor growth and invasion, Cxcr2 particularly with angiogenic processes." (PMID 24156623, 2013). "In conclusion, our results showed that stromal CXCR2 levels were correlated with high grade breast tumors and TNBC phenotype as previously reported for its ligands." (PMID 32727083, 2020). "In this study, we aimed to understand the potential involvement of the chemokine receptor CXCR2 in the breast tumor microenvironment." (PMID 32727083, 2020). "Ginestier and colleagues also showed that blocking of both the receptors for IL8, CXCR1, and CXCR2, by treatment with the drug repertaxin, significantly reduced the formation of bone metastasis after intracardiac injection of breast tumor cells in mice." (PMID 23113900, 2012). "A study reported that macrophage-derived CXCR2 might be crucial in promoting FGFR signaling-regulated breast tumor formation." (PMID 40722739, 2025). "While the results thus far focused on the individual modalities of tumor-related neutrophil functionalities, we sought to simulate the effects of CXCR2 activation on the wholesome neutrophil behavior within a breast tumor microenvironment consisting of brain-tropic metastatic variants." (PMID 35158784, 2022). "Similarly, within the luminal B subtype, CXCR2 expression is lower in Black and Asian compared to White patient breast tumors." (PMID 35754051, 2022). "Moreover, we have recently shown that CXCR2 levels were also increased in human TNBC compared to luminal breast tumors, as shown for other types of cancers." (PMID 34070438, 2021). "Whereas, this study indicated that signaling via CXCR2 has increased the senescence of luminal-A breast tumor cells, in another study opposite findings were found, demonstrating that CXCR2 down-regulated senescence of breast tumor cells, including of the luminal-A subtype." (PMID 32582148, 2020). "In breast tumours, TGF-α is activated in MSCs to recruit CXCR2+ neutrophils and promote the metastasis of breast tumours." (PMID 35869057, 2022). "While CXCR2 KO mice decreased MDSCs in breast tumors, adipose-specific CXCR2 cKO mice had no change in omental tumor tissues of OC." (PMID 34638514, 2021). "Focusing on breast tumors, we reported that CXCR2, CD11b or CD66b expression was not correlated to the age of patients, the histological type (ductal carcinoma versus others), the size of the tumors, or lymph node status." (PMID 32727083, 2020). "We observed that CXCR2 was more expressed in breast tumors than in a normal breast, whereas CD11b was present at lower levels in breast tumors and CD66b was not different between normal and cancer tissues." (PMID 32727083, 2020). "We also previously showed at the mRNA level that breast tumor cells did not express significant levels of CXCR2 mRNA." (PMID 32727083, 2020). "Similarly, CXCR2 expression is not consistently found to be highly expressed in cancer cells within breast tumors, but rather this receptor is most highly expressed in the stromal cells of breast tumors, particularly neutrophils." (PMID 35754051, 2022).
Hypertension (19 papers, 2019 to 2025). The presence of chronic increased pressure in the systemic arterial system. "Another important point is that CXCR2 also plays an important role in hypertension, vascular dysfunction, and cardiac remodeling associated with the disease." (PMID 40859641, 2025). "We found that CCL5 and CXCR2 polymorphisms were associated with increased cancer risk, while the relationships remained significant after adjustments for age, diabetes, hypertension, or endometrial thickening." (PMID 38001676, 2023). "According gene–gene interaction analysis, Timasheva’s group illustrated that the loci of CXCR2 is significantly associated with stroke development in patients with hypertension." (PMID 30760287, 2019). "Several studies suggest that CXC chemokines, such as CXCL1, and their receptor CXCR2 are strongly associated with the migration and recruitment of monocytes/macrophages and neutrophils in different inflammatory diseases, including hypertension, cardiac remodelling, and atrial fibrillation." (PMID 35981418, 2022). "Therefore, therapeutic targeting of the KLF15 or CXCL1/CXCR2 axis may serve as an innovative approach for the treatment of hypertension-associated cardiovascular disease." (PMID 33869197, 2021). "While CXCR2 antagonists show promise in reducing hypertension, their beneficial effects likely arise from actions on immune cells." (PMID 40859641, 2025). "In murine models, knock-out or blocking of CXCR2 reduced angiogenesis, neutrophil infiltration into, and the size of an infarcted area or prevented experimental hypertension and vascular dysfunction by reducing the recruitment of CXCR2+ pro-inflammatory cells." (PMID 36725964, 2023). "Blockade of CXCL1/CXCR2 signaling attenuated KLF15 deficiency-induced accelerated cardiac remodeling, which provides a new KLF15/CXCL1 axis in regulation of hypertension-associated cardiac remodeling." (PMID 33869197, 2021). "Recently, it has been reported that the CXCL1/CXCR2 axis is essential for recruitment of monocytes and macrophages into hearts and arteries in hypertension." (PMID 33869197, 2021). "For example, the chemokine receptor CXCR-2 is a key regulator of monocyte mobilization in hypertension and heart remodeling; and blocking the activation of CXCR-2 can be used as a new treatment strategy for AF." (PMID 34671599, 2021). "In conclusion, our study identifies that KLF15 in cardiac fibroblasts negatively regulates CXCL1/CXCR2 axis-mediated inflammatory response and subsequent cardiac remodeling in hypertension." (PMID 33869197, 2021). "Recently, we demonstrated that the chemokine‐receptor CXCR2 plays a critical role in the recruitment of monocytes/macrophages and the development of hypertension and cardiac remodelling." (PMID 32812337, 2020). "Pharmacological inhibition of CXCR2 using SB225002 prevented and even reversed hypertension‐induced AF susceptibility and atrial remodelling in SHRs, likely though the inhibition of macrophage infiltration and oxidative stress." (PMID 32812337, 2020). "Increased IL-8 binding to CXCR2 has been shown to reduce vascular wall thickness, which can worsen hypertension decrease in the area covered by the vasculature." (PMID 32766248, 2020). "In conclusion, this study identified an important functional role of CXCR2 in promoting macrophage recruitment into the atria of SHRs, leading to atrial remodelling and AF inducibility after hypertension." (PMID 32812337, 2020). "Suppression or knockdown of CXCR2 inhibited Ang II-induced hypertension." (PMID 34385934, 2021). "Moreover, our recent data indicate that the up‐regulation of CXCL1 or CXCR2 contributes to the Ang II‐induced recruitment of monocytes and macrophages, hypertension, vascular injury and cardiac hypertrophic remodelling." (PMID 32812337, 2020).
Hypertension (continued). "In the present study, we found that hypertension stimulated CXCR2 activation, which activated several downstream signalling pathways, including NF‐κB, NADPH oxidase and TGF‐β1/Smad2/3, which promoted pro‐inflammatory, pro‐oxidative and pro‐fibrotic effects that led to AF." (PMID 32812337, 2020). "In addition, in SHR animals, the BP increasing in this model has a certain link with the infiltration of macrophages in the cardiovascular system, and the deletion of the CXCR2 gene in mice attenuates hypertension, reduces monocyte infiltration in the heart, and improves cardiac remodeling." (PMID 40859641, 2025). "Besides, CXCR2 can play a role in myocardial ischemia/infarction and arterial hypertension." (PMID 36725964, 2023). "Moreover, CXCR2 is also a crucial regulator of hypertension." (PMID 35305619, 2022). "C-X-C Motif Chemokine Ligand 1(CXCL1)/CXCR2 biological axis plays an important role in the modulation of theadhesion and aggregation of macrophages in the aortic wall, and mediates theinflammatory response in vascular diseases such as hypertension andatherosclerosis." (PMID 33605308, 2021). "However, whether CXCR2 mediates the infiltration of monocytes and the initiation of AF secondary to hypertension is unclear." (PMID 32812337, 2020). "The literature mainly highlights the receptors CCR2, CCR5, CXCR1, CXCR2, and CXCR4 as the most relevant for the progression of hypertension." (PMID 40859641, 2025). "Studies showed that biomarkers include PLD2, FLNA (filamin A), SMURF1, LINGO1, CACNA1H, NLRP6, NLRC3, CXCR2 and C5AR1 plays an important role in progression of hypertension." (PMID 36837510, 2023). "To determine whether CXCL1 and CXCR2 are associated with HR in humans, we examined serum CXCL1 levels and the number of CXCR2+ immune cells as well as other related risk factors in healthy controls (n = 40) and patients with HR (n = 40) and hypertension (HP, n = 40)." (PMID 35981418, 2022). "Pharmacological blockage of CXCR2 by SB225002 significantly prevented and suppressed the development of AF, likely by inhibiting the hypertension‐induced recruitment of macrophages into the atria and oxidative stress in SHRs." (PMID 32812337, 2020). "The blockage of CXCR2, the receptor of CXCL1, could suppress hypertension and end-organ damage in SHR and other hypertensive animal models." (PMID 33532132, 2021). "In contrast, another study shows an increase in circulating CXCR2-expressing G-MDSCs but not M-MDSCs in IPF, as well as in mouse models of lung fibrosis and hypertension." (PMID 36045668, 2022).
diabetes (17 papers, 2009 to 2026). "Moreover, CXCR2-deficient mice are resistant to diet-induced insulin resistance and diabetes, mainly because CXCL5 blocks insulin signaling in muscle by activating the muscle Jak/STAT/SOCS pathway through the CXCR2 receptor." (PMID 32377527, 2020). "Animal experiments revealed that diabetes upregulated the expression of CXCR2 in hepatic neutrophils, thereby promoting the formation of neutrophil extracellular traps (NETs)." (PMID 41698066, 2026). "The protective effect of CXCR2 blockade on diabetes development was replicated with two additional blockers." (PMID 40718478, 2025). "The observation that CXCR2 (−/−) mice are resistant to diet-induced insulin resistance and diabetes prompted numerous studies aimed at clarifying the neutrophil-dependent and independent mechanisms implicated." (PMID 34571976, 2021). "Subsequently, we observed that the expression of CXCL1 and its receptor (CXCR2) was significantly increased in the kidneys of mice with HFD + STZ induced diabetes and DN patients." (PMID 34975537, 2021). "We show that inhibition of theCXCL5-CXCR2 axis, both by CXCR2 antagonists or CXCL5 blocking antibodiesdecreases glycemia in mice models of diabetes." (PMID 20157549, 2009). "Further investigation into the IL-8-CXCR1/CXCR2 axis could provide insights into its role in regulating Bregs and its potential as a therapeutic target in diabetes." (PMID 40370441, 2025). "Indeed, serum levels of IL-8 are increased in T2D patients, and CXCR2 (−/−) mice are resistant to diet-induced insulin resistance and diabetes." (PMID 34571976, 2021). "Simultaneously, severe immune cell infiltration of Mpo and Cxcr2 along with elevated levels of Fn1 might have antagonized damage in the diabetic pancreas." (PMID 26110898, 2015). "Importantly, the blockade of neutrophils recruitment in the neonatal NOD mice using a CXCR2 antagonist dampens the diabetogenic T-cell response, the insulitis, and the incidence of diabetes." (PMID 24968718, 2014). "Ladarixin, an allosteric non-competitive CXCR1 and CXCR2 antagonist, delayed the onset of diabetes and improved glycemic control when administered following multiple low-dose STZ injections in C57BL/6 mice." (PMID 40718478, 2025). "However, comparable levels of PECAM1, CXCR2, SLC2A3, BST2, S100A11, S100A12, and CPNE3 were found in neutrophils from diabetes patients and controls (P > 0.05)." (PMID 32377527, 2020). "Chronic inflammation occurred in the diabetic pancreas accompanied by up-regulation of CCAAT/enhancer-binding protein beta (C/EBPβ) and its targets (TNFα, Il6, CRP, and Fn1) as well as myeloperoxidase (Mpo) and C-X-C chemokine receptor type 2 (Cxcr2)." (PMID 26110898, 2015). "It is noteworthy that CXCR2 blockage at later age (between 8 and 10 weeks of age) did not affect subsequent diabetes development." (PMID 24968718, 2014). "In addition, a related compound, ladarixin, which has equivalent selectivity for CXCR1 and CXCR2 and is orally bioavailable, can delay diabetes onset in non-obese diabetic mice and is currently in a phase 2 clinical trial for new-onset diabetes type 1 (NCT02814838, ClinicalTrials.gov)." (PMID 41176546, 2025).
liver cancer (17 papers, 2014 to 2025). An epithelial or non-epithelial malignant neoplasm that arises from the liver. "In summary, this study demonstrates a strong association between elevated CXCL3 expression and the accumulation of immune cells and CXCR2-associated chemokines within the tumor microenvironment of liver cancer." (PMID 41259383, 2025). "It has been reported that the IL-8 receptors CXCR1 and CXCR2 are highly expressed in HepG2, Huh7, and other liver cancer cells." (PMID 41081508, 2025). "In this study, serum IL-8 levels in patients with primary liver cancer were significantly higher than those in healthy controls, and its level was higher in patients with low CXCR2+ monocytes percentage." (PMID 37403022, 2023). "To determine the functional relevance of this finding, we reanalyzed Hoshida Golub Liver GSE10143 (n = 162) data and demonstrated that the high expression of CXCR2 and CXCL6 was associated with worse overall survival in patients with liver cancer." (PMID 37509721, 2023). "The association between the expression of genes in the CCL2/CCR2 and CXCL8/CXCR2 axes and patient OS in the TCGA liver cancer dataset was analyzed." (PMID 36403057, 2022). "The results showed that CCL2, CCR2, CXCL8, and CXCR2 were more highly expressed in adjacent normal tissues than in liver cancer tissues." (PMID 36403057, 2022). "The CXCR2 axis has been reported to induce angiogenesis in liver cancer mouse models via IL-17A." (PMID 41155662, 2025). "Since both CXCL3 and CXCL5 signal through CXCR2, it is plausible that CXCL3 may also promote liver cancer progression via CXCR2-dependent pathways." (PMID 41259383, 2025). "Interleukin-8 promotes cell migration via CXCR1 and CXCR2 in liver cancer." (PMID 33336008, 2020). "Notably, IL-17A promotes CXCR2-dependent angiogenesis in liver cancer." (PMID 36980564, 2023). "Hence, although CXCR2 antagonism alone delivered modest model-dependant antitumour benefit, similar to observations made in models of non-hepatic cancers, we show that CXCR2 inhibition sensitises to anti-PD1 immunotherapy in models of NASH-HCC that are otherwise resistant to anti-PD1 monotherapy." (PMID 35477863, 2022). "Here, we evaluated the feasibility of targeting CCR2 and CXCR2 with their respective antagonists INCB3344 and SCH527123 for liver cancer therapy." (PMID 36403057, 2022). "To further confirm these results, we compared the expression levels of the CCL2/CCR2 and CXCL8/CXCR2 genes in HCC tumors and adjacent normal tissues using data from the TCGA liver cancer database." (PMID 36403057, 2022). "CXCR2 was also documented to be correlated with intrahepatic metastasis, portal cancer embolus and TNM staging of liver cancer patients, although the role of CXCR2 in tumor cells is debated." (PMID 25011526, 2014). "For example, IL-8 promotes the migration of liver cancer cells through CXCR1 and CXCR2, and targeting CXCR1/2 may be a strategy for treating liver cancer." (PMID 34516330, 2021). "Using a cell coculture system (Transwell), we cocultured Huh7 liver cancer cells and THP-1 monocytes with and without CXCL6/CXCR2 small interfering RNA for 72 h." (PMID 37509721, 2023).
esophageal cancer (16 papers, 2014 to 2025). A primary or metastatic malignant neoplasm involving the esophagus. "Other chemokines such as CXC chemokine type 2 (CXCR2) seem to be involved in lymphangiogenesis, as a high expression of CXCR2 is associated with increased lymph node metastases and a reduced prognosis in resected esophageal carcinoma." (PMID 25254213, 2014). "To further clarify the critical role of chemokines in suppressing p-FGFR1Y654expression, we analyzed the mutations of all chemokines in esophageal cancers using the GSCA database mutation module and found that CXCR2 exhibited the highest mutation rate." (PMID 40722739, 2025). "Using the TCGA database, we confirmed that both CXCR2 and CXCL8 are overexpressed in ESCC, whereas CXCL8 exhibited a high diagnostic value for esophageal cancer (AUC: 0.95, 95% CI: 0.893–1.000)." (PMID 40722739, 2025). "Second, the activation of CXCR2 results in increased expression of early growth response-1 (EGR-1) in esophageal cancer, which increases proliferation by elevating the expression of cyclin-dependent kinase 4 (CDK4)." (PMID 35216283, 2022). "Our previous investigations indicated the significant differences between serum levels of CXCL8 and/or CXCR2 in cancer patients and healthy individuals; however, these studies were performed on pancreatic, colorectal as well as esophageal cancer patients." (PMID 34680333, 2021). "Our study also demonstrated that CXCR2 expression in esophageal cancer was significantly correlated with the site of recurrence." (PMID 26231560, 2015). "In conclusion, we demonstrated that the patients with CXCR2-positive esophageal cancer who develop postoperative complications have a poor prognosis and should be carefully followed." (PMID 26231560, 2015). "Our results suggest that the patients with CXCR2-positive esophageal cancer who develop postoperative complications have a poor prognosis and should be carefully followed." (PMID 26231560, 2015). "The CXCL1/CXCR2 axis has been shown to participate in the regulation of ERK1/2 phosphorylation in esophageal cancer, which is responsible for the transcription of the EGR-1 gene, the crosstalk of among CXCL1/CXCR2 axis, ERK1/2 and EGR-1 result in a rapid increase in tumor cell proliferation." (PMID 35764974, 2022). "Other studies revealed had no obvious association of CXCR2 with the outcomes of esophageal cancer, pancreatic ductal cancer, or ovarian cancer." (PMID 29312644, 2017). "CXCR2 expression was downregulated in BLCA, lymphoid neoplasm diffuse large B-cell lymphoma (DLBC), esophageal carcinoma (ESCA), head and neck squamous cell carcinoma (HNSC), lung adenocarcinoma (LUAD), skin cutaneous melanoma (SKCM), and thymoma (Thymoma) subjects." (PMID 34692853, 2021). "MIF serves as a non-cognate ligand for CXCR2 and CXCR4: MIF (and CXCR4) in the TME are adverse prognostic indicators in esophageal cancer, and it can induce CXCR ligand and regulators of macrophage infiltration like CD44." (PMID 26267609, 2015).